BRCA1 (BRCA1 DNA repair associated)
Diseases named in the same sentence as BRCA1 in open-access papers (continued):
Sharing a sentence is not in itself a finding about the gene and the disease.
breast cancer (continued). "In a study analyzing 531 breast cancer patients, BRCA1-633delC was detected with relatively higher prevalence in patients with TNBC, whereas BRCA2-1466delT was found mainly in luminal B tumors." (PMID 34202525, 2021). "Histone modification and DNA methylation of MGMT, BRCA-1, and P16 were assessed in a sample of Iranian breast cancer patients." (PMID 33883026, 2021). "On the contrary, BRCA1 deregulation, which is universal for breast cancer patients, facilitates the interaction and enhances PRC2-mediated H3K27me3 on specific gene sites, and thus, tumor progression is initiated." (PMID 34073224, 2021). "There were 108 breast cancer deaths (many had breast cancer before genetic testing) and 13 other cancer deaths likely to be unrelated to BRCA1/2." (PMID 33152107, 2021). "As previously reported, breast cancer is the most common malignancy in individuals with BRCA1 or BRCA2 germline PVs and the ductal histotype was more frequent than others." (PMID 34572941, 2021). "A case–control study found evidence for an independent association of PC risk with PGVs in six genes: ATM, BRCA1, BRCA2, CDKN2A, MLH1, and TP5316, five of which (excluding CDKN2A) have a clear link to breast cancer risk." (PMID 34127761, 2021). "This study evaluates the prevalence of germline mutations in BRCA1 and BRCA2 among breast cancer patients diagnosed at age 40 or younger in Jordan." (PMID 34290354, 2021). "A celebrity’s announcement of having a BRCA1 mutation and undergoing bilateral risk-reducing mastectomy (RRM) has influenced breast cancer patients and women with high-risk breast cancer." (PMID 34285295, 2021). "BRCA1 and BRCA2 mutation play an important role in genetic susceptibility of breast cancer progression." (PMID 33968766, 2021). "By using these mutant mice along with human BRCA1 deficient as well as proficient breast cancer tissues and cells, we investigated and compared the role of Brca1 and Gata3 loss in the activation of EMT in breast cancers." (PMID 34373738, 2021). "Drugs that target this pathway have been clinically validated in patient subgroups, such as the use of PARP (poly ADP-ribose polymerase) inhibitors to treat BRCA1/BRCA2 mutant breast cancer patients." (PMID 33832493, 2021). "Most research on checkpoint inhibitors in breast cancer has focused on patients with TNBC, a subgroup that is enriched for BRCA1 mutations." (PMID 34067105, 2021). "For BRCA1, BRCA2, and other genes associated with breast cancer, there is also an impact of population ancestry and potential modifier alleles." (PMID 34584094, 2021). "In our study, the upregulated expression and prognostic value of these hub genes in BRCA1/2-mutant BC suggested that its roles in this type of breast cancer were equally noteworthy." (PMID 34733851, 2021). "Our finding, for the first time, demonstrates that GATA3 functions downstream of BRCA1 to suppress EMT in controlling mammary tumor initiation and metastasis." (PMID 34373738, 2021). "Both of these patients were diagnosed with bilateral breast cancer and both carried a mutation in the PALB2 gene.a- for BRCA1, CHEK2, PALB2, NBN mutation frequencies in cancer-free controls were from our previous studies." (PMID 34461861, 2021). "Prompted by the finding that Gata3 functions downstream of Brca1 in suppressing EMT in breast cancers, we then examined if ectopic Gata3 in Brca1-deficinet tumor cells suppresses their potential for tumor initiation and metastasis." (PMID 34373738, 2021). "In Japan, BRCA1/2 genetic testing has been covered by the National Medical Insurance only for companion diagnostics for patients with HER2-negative recurrent breast cancer since 2018." (PMID 34674065, 2021).
breast cancer (continued). "We have undertaken panel testing beyond BRCA1/2 in 1398 patients with breast cancer and identified 95 (6.3%) with actionable breast cancer genes." (PMID 34439310, 2021). "Most women with the BRCA1 mutations who develop breast cancer have triple negative breast cancer, while those with BRCA2 mutations end up with ER+ and/or PR+ forms of breast cancer." (PMID 34171558, 2021). "In particular, BRCA1 and BRCA2 mutation carriers have a 60–65% and 45–55% risk of breast cancer up to the age of 70 years, respectively." (PMID 34575624, 2021). "Fifty-five to sixty-five percent of women with BRCA1 mutation and 45% of women with BRCA2 mutations will develop breast cancer by the age of 70 years." (PMID 33578759, 2021). "Studies of breast carcinoma have determined that reduced expression of HRR genes, such as BRCA1 and RAD51C, primarily via promoter methylation, associates with mutational signatures of HRRd." (PMID 34877933, 2021). "Heterozygous mutation of BRCA1 and BRCA2 genes alongwith PALB2 contribute to high risk female breast cancer and ovarian cancer." (PMID 34092963, 2021). "The only triplication of BRCA1 exons described up to now covering exons 17 to 19 was only found in a small family presenting a woman diagnosed for breast carcinoma at 31 years old." (PMID 34202044, 2021). "In human breast carcinoma cells, BRCA1 increases activity of select enzymes involved in the earlier stages of the base excision repair pathway." (PMID 34222870, 2021). "In sporadic breast carcinomas and in sporadic ovarian carcinomas, Brca1 promoter methylation was found in 5.8–35.7% and in 12.3 to 22.5% of the cases, respectively." (PMID 34681626, 2021). "To further verify the relationship between BRCA1 and glucose dependence or consumption in breast cancer cells, we knocked down BRCA1 in MCF-7 and MDA-MB-231 cell lines and repeated above experiments." (PMID 32470015, 2020). "With defective homologous recombination DNA repair, BRCA1- and BRCA2-mutated breast cancers are targets for PARPi through the exploitation of synthetic lethality." (PMID 33257598, 2020). "Approximately 57% of women with an inherited BRCA1 pathogenic variant and 49% with a BRCA2 pathogenic variant develop breast cancer by 70 years of age, compared to a lifetime risk of 12.5% in women in the general population." (PMID 32518611, 2020). "Previous studies reported that 4–40% and 0–11% of patients with male breast cancer harbored BRCA2 and BRCA1 mutations, respectively." (PMID 33054725, 2020). "This study uncovers the function of BRCA1 in regulating mitophagy and provides a rational approach for treating BRCA1 mutant breast cancer with inflammasome inhibitors." (PMID 32195105, 2020). "BRCA1 and BRCA2 mutations have been found in 5–10% of all breast cancers and in up to 20–25% of tumors in patients with a family of breast and/or ovarian cancer." (PMID 33019612, 2020). "Due to the association of BRCA1 and BRCA2 proteins with telomere maintenance, peripheral blood was collected from 40 women (31 with breast cancer) and telomere-associated gene expression levels were assessed." (PMID 33081408, 2020). "The odds ratios for breast cancer diagnosed at age 40 or below were 28.8 for BRCA1 (95% CI 18.6–44.5); 3.8 for CHEK2 (95% CI 2.5–5.5); and 3.6 for PALB2 (95% CI 1.6–7.5), and all were statistically significant." (PMID 32824581, 2020). "While, for the molecular subtype of breast cancer we found a correlation between BRCA1/2 carriers and triple negative breast cancer with a P-Value < 0.05." (PMID 32778078, 2020). "We have shown previously in breast cancer cells cultured in high glucose that IGF-I reduced the interaction between BRCA1 and phosphorylated ACCA and that it induced cell growth in a FASN-dependent manner." (PMID 33212987, 2020).
breast cancer (continued). "The breast cancer prospective cohort included 2088 BRCA1 carriers with 297 incident cases and 1757 BRCA2 carriers with 215 incident cases." (PMID 32665703, 2020). "In BRCA1 carriers from CIMBA, RA showed a statistically significant decrease in breast cancer risk (OR: 0.96, 95% CI: 0.95–0.97)." (PMID 33167385, 2020). "More intriguingly, in addition to the tissue preference, BRCA1 and BRCA2 mutation carriers tend to develop different kinds of breast cancer." (PMID 33299637, 2020). "BRCA1, along with BRCA2, is a breast cancer susceptibility gene and a well-known tumor suppressor gene that displays an autosomal dominant pattern of inheritance accompanied by high penetrance." (PMID 31830649, 2020). "In contrast, approximately 72% of women who inherit a pathogenic BRCA1 mutation and 69% of women who inherit a pathogenic BRCA2 mutation will develop breast cancer by the age of 80." (PMID 32620799, 2020). "Our data suggest that young age (≤ 40 years) irrespective of family history is a sufficient criterion for systematic genetic screening for Moroccan young breast cancer patients, following the western recommendations for BRCA1/2 genetic testing." (PMID 32894085, 2020). "Cancer predisposition genes, BRCA1 and BRCA2, were first discovered in the genetic study on familial breast cancer." (PMID 32269964, 2020). "Some evidence points to downregulation of BRCA1, an important tumor suppressor in mammary cancer, in canine mammary samples." (PMID 33194754, 2020). "A systematic review of the cost-effectiveness of healthcare programs involving genetic testing of the two major breast cancer genes, BRCA1 and BRCA2 indicated that family history-based screening programs are cost-effective." (PMID 32231682, 2020). "For example, results in breast cancer showed that organoids with high BRCA1/2 signature responded to PARP inhibitors treatments, whereas organoids with low BRCA1/2 signatures did not." (PMID 31991800, 2020). "Inactivation of BRCA1 or BRCA2 is associated with a pattern of genome-wide mutations known as signature 3, which is strongly associated with breast cancers." (PMID 33324554, 2020). "The prevalence and clinical outcome of germline mutations in the BRCA1/2 and/or PALB2 genes in breast cancer patients in different ethnic groups, including populations from Turkey, Lebanon, Japan, Mexico, China, etc, have been widely reported recently." (PMID 31782247, 2020). "Among all biological subtypes of breast cancer, triple-negative breast cancer (TNBC) is more likely to harbor a germline BRCA1/2 mutation, with reported prevalence rates varying from about 10% to 20%." (PMID 32322271, 2020). "The C61G mutation in the BRCA1 RING domain is the most frequently initiated missense variant, which is highly associated with ovarian and breast cancer." (PMID 33324554, 2020). "Especially mutations in the BReast CAncer genes BRCA1 and BRCA2, which are key genes for the regulation and repair of DNA, increase the risks for breast cancer to 55–60% and for ovarian cancer to 16–59% by age 70 years in women." (PMID 32532068, 2020). "In clinical practice, BRCA1/2 are the most widely tested genes, particularly for breast cancer patients diagnosed at young age, with triple negative breast cancer (TNBC), or have a significant family history of breast, ovarian, or other related cancers." (PMID 32091409, 2020). "Two variants (BRCA1 c.3257del and c.440del) were specific in breast cancer cases, while BRCA2 c.7409dup and c.4307T>C were detected in two hepatocellular carcinoma patients and the BRCA1 c.4801A>T variant in one cervical cancer patient, respectively." (PMID 32879886, 2020). "In this study, we evaluate the pattern and prevalence of germline mutations in BRCA1 and BRCA2 among high-risk Jordanian breast cancer patients selected as per international guidelines." (PMID 32733560, 2020).
breast cancer (continued). "Discovery of the breast cancer 1 (BRCA1) and breast cancer 2 (BRCA2) genes led to the development of genetic tests to identify individuals at risk for hereditary breast and ovarian cancer (HBOC)." (PMID 31963545, 2020). "We analyzed BRCA1 promoter methylation by pyrosequencing DNA from tumor samples from 1031 patients with primary breast cancer." (PMID 32175521, 2020). "Although some genes have been identified and the pathogenic mechanism of BRCA1/2 genes for breast cancer has partly explained, the closely related genes to BRCA1/2 in breast cancer (BC) remain to be fully elucidated." (PMID 31998560, 2020). "Preclinical data also showed that DHA treatment increases BRCA1 protein level by 60% compared to an unsupplemented group and significantly reduced the incidence of breast cancer, potentially signifying a protective effect." (PMID 32498320, 2020). "We found weak evidence for the association of risk variants rs294174 (ESR1), rs16886165 (MAP3K1), rs2214681 (CNTNAP2), rs4237855 (VDR), rs9594579 (RANKL), rs8183919 (PTGIS), rs2981582 (FGFR2), and rs1799950 (BRCA1) with sporadic breast cancer." (PMID 33126731, 2020). "Accordingly, the level of these key proteins is correlated with BRCA1 status in breast cancer cell lines and in patient breast tumors." (PMID 32290274, 2020). "A literature review of the plausible target genes indicated that similar biological functions underscored the genetic survival associations of BRCA1 and BRCA2 carrier breast cancer patients." (PMID 32964118, 2020). "To understand the molecular mechanism by which IR induced PRMT1-dependent methylation of BRCA1 in breast cancer cells, we first analyzed the effect of IR on PRMT1 expression at both the protein and mRNA levels." (PMID 32764667, 2020). "By restricting our analysis to CMF–treated patients only, we find that the relation between BRCA1 methylation and breast cancer–specific survival holds statistical significance (HR = 0.11, 95% CI = 0.014 to 0.81, P = .03)." (PMID 32175521, 2020). "Among these genes, BRCA1 and BRCA2, as well-known tumor suppressor genes, were associated with breast cancer risk, which was identified from 1994 to 1995." (PMID 32879886, 2020). "A meta-analysis reported that 5- and 10-year cumulative risks of contralateral breast cancer were 15% and 27% respectively in BRCA1 PV carriers." (PMID 32045981, 2020). "Mutations in BRCA1 and BRCA2 genes represent a significant independent risk factor for ovarian and breast cancer." (PMID 32719921, 2020). "Materials and Methods: We retrospectively reviewed medical records of 300 patients with breast cancer who underwent genetic screening for BRCA1/2 genes and were treated at Samsung Medical Center between 1 January 2000 and 31 December 2010." (PMID 33019612, 2020). "The estimated risk up to 80 years of age for ovarian and breast cancer among women with BRCA1 and BRCA2 pathogenic germline gene variants is 44 and 72% respectively for BRCA1 and 17 and 69% respectively for BRCA2." (PMID 32165993, 2020). "Most cases of breast cancer related to BRCA1 and BRCA2 are diagnosed in young women, and the probability of pregnancy in young women is high." (PMID 33379383, 2020). "BRCA1 is a tumor suppressor gene that is closely related to breast cancer, ovarian cancer, and other hormone-related cancers and plays a negative regulatory role in tumor growth." (PMID 33817238, 2020). "Among BRCA1 carriers, the average lifetime cancer risks are 67% for breast cancer and 45% for ovarian cancer." (PMID 36312308, 2020). "Women with pathogenic germline gene variants in BRCA1 and/or BRCA2 are at increased risk of developing ovarian and breast cancer." (PMID 32165993, 2020).
breast cancer (continued). "The prevalence of MF/MC disease was 13.3% amongst BRCA1 mutation carriers diagnosed with breast cancer, and 47.1% amongst BRCA2 mutation carriers diagnosed with breast cancer." (PMID 32022473, 2020). "Down-regulated expression levels of MCM2 (mini-chromosome maintenance complex component 2), PARP1, and BRCA1 (breast cancer type 1) genes in CBD-treated HNSCC were confirmed by quantitative real-time RT-PCR and then compared with the RNA-seq results." (PMID 33244087, 2020). "Low levels of BRCA1 expression are detected in ~30% of sporadic breast cancers, possibly due to hypermethylation of the promoter or other transcriptional regulatory mechanisms." (PMID 32591500, 2020). "Among them, CCNE1 and KRT20 were of high expression in BRCA1/2-mutant breast cancer, and ALB and MYOM2 were of low expression." (PMID 31998560, 2020). "Several pre-clinical studies have shown that PARPis are able to inhibit cell growth and promote the death of breast cancer cells that are wild type for BRCA1/2." (PMID 32605126, 2020). "Data from 211 women with BRCA1/2 mutations (BRCA1‐91, BRCA2‐120) and breast cancer were collected including age, tumour focality, size, type, grade and receptor profile." (PMID 32022473, 2020). "Therefore, these miRNAs could be useful as potential diagnostic biomarkers to improve the performance of the BRCA1/2-mutation prediction models and impact on the clinical management of breast cancer patients who may benefit from platinum-based chemotherapy and PARP inhibitors, such as olaparib." (PMID 32087690, 2020). "BReast CAncer genes-1/-2 (BRCA1/2) are the most common genes implicated in BC risk." (PMID 33716731, 2020). "Complementarily, Brca1F/F Trp53F/F Krt14-Cre mice develop mammary tumors (designated as BRCA1-null tumors) which mimic basal-like breast cancers and were ER-/PR-/HER-." (PMID 32840210, 2020). "The actionable advantages of knowing one’s genetic status, which can be used to guide treatment, early detection, and risk-reducing (RR) strategies, have prompted support for the universal BRCA1/2 testing of all breast cancer patients." (PMID 33110458, 2020). "Management ranges from altered surgical and adjuvant approaches for women with BRCA1 and BRCA2 mutations, to enhanced surveillance for women with mutations in moderate-penetrance breast cancer genes or in genes associated with risk of other types of cancer." (PMID 31963545, 2020). "When compared to a set of randomly selected PBMCs, ClearCell Polaris captured cells showed elevated expression of breast cancer-specific markers BRCA1 and MDM2 (p-value < 0.05)." (PMID 32331451, 2020). "For example, in our study, the gene contributing most to the breast cancer risk was BRCA2 while in studies of European ancestry or African ancestry, it was BRCA1." (PMID 32318955, 2020). "We have demonstrated in this study that metastatic TNBC cells, MDA-MB-436 (BRCA1- deficient), MDA-MB231, and MDA-MB-468, were all sensitive to Talazoparib, a PARPi that has been approved to treat HER2- breast cancer with BRCA-mutations." (PMID 32235451, 2020). "The aetiology of BC in the region, including Qatar encompasses numerous risk factors such as late menopause, prolonged hormone replacement therapy, older age at first live childbirth, family history of BC at a young age and the mutations of the breast cancer associated gene 1 and 2 (BRCA1/2) genes." (PMID 32888398, 2020). "While hereditary genetic mutations lead to approximately 10 to15% of breast cancer cases, the mutations in BRCA1 and BRCA2 (BRCA) genes are the most penetrating mutations that cause breast cancer." (PMID 32070378, 2020). "Conditional Brca1 knockout mice have been established to study the role of Brca1 in breast cancer development." (PMID 32785175, 2020). "BRCA1 is a genetic marker for breast cancer, and its role in the DNA damage repair mechanism has been demonstrated." (PMID 32325967, 2020).